RN7SL705P (RNA, 7SL, cytoplasmic 705, pseudogene)
Gene: Miscellaneous RNA gene on chromosome 18 (62,650,308 to 62,650,601, reverse strand). Ensembl gene ENSG00000243549.
Homologues: Orthologues: chimpanzee Metazoa_SRP (91% identical), macaque Metazoa_SRP (90% identical). Paralogues in human: RN7SL1 (80% identical), RN7SL2 (80% identical), RN7SL3 (80% identical), RN7SL218P (79% identical), RN7SL397P (78% identical), RN7SL126P (78% identical), RN7SL559P (78% identical), RN7SL296P (78% identical), RN7SL178P (77% identical), RN7SL186P (77% identical), RN7SL660P (77% identical), RN7SL778P (77% identical), and 702 more.